TRAV8-3 (T cell receptor alpha variable 8-3)
Description:
V region of the variable domain of T cell receptor (TR) alpha chain that participates in the antigen recognition. Alpha-beta T cell receptors are antigen specific receptors which are essential to the immune response and are present on the cell surface of T lymphocytes. Recognize peptide-major histocompatibility (MH) (pMH) complexes that are displayed by antigen presenting cells (APC), a prerequisite for efficient T cell adaptive immunity against pathogens. Binding of alpha-beta TR to pMH complex initiates TR-CD3 clustering on the cell surface and intracellular activation of LCK that phosphorylates the ITAM motifs of CD3G, CD3D, CD3E and CD247 enabling the recruitment of ZAP70. In turn ZAP70 phosphorylates LAT, which recruits numerous signaling molecules to form the LAT signalosome. The LAT signalosome propagates signal branching to three major signaling pathways, the calcium, the mitogen-activated protein kinase (MAPK) kinase and the nuclear factor NF-kappa-B (NF-kB) pathways, leading to the mobilization of transcription factors that are critical for gene expression and essential for T cell growth and differentiation. The T cell repertoire is generated in the thymus, by V-(D)-J rearrangement. This repertoire is then shaped by intrathymic selection events to generate a peripheral T cell pool of self-MH restricted, non-autoaggressive T cells. Post-thymic interaction of alpha-beta TR with the pMH complexes shapes TR structural and functional avidity.
Synonyms: TCRAV1S4; TCRAV8S3; TRAV83
Gene: T-cell receptor variable (V) gene on chromosome 14 (21,852,558 to 21,853,006, forward strand). Ensembl gene ENSG00000211787.
Subcellular location: Cell membrane
Gene Ontology:
Biological process: adaptive immune response
Cellular component: immunoglobulin complex; plasma membrane
Homologues: Orthologues: macaque TRAV8-3 (78% identical), mouse Trav9-4 (76% identical), mouse Trav9-2 (74% identical), mouse Trav9d-3 (74% identical), mouse Trav9n-3 (74% identical), mouse Trav9n-4 (74% identical), mouse Trav9d-2 (73% identical), mouse Trav9n-2 (73% identical), mouse Trav9d-4 (69% identical), mouse Trav9-1 (65% identical), mouse Trav9d-1 (64% identical). Paralogues in human: TRAV8-1 (74% identical), TRAV8-4 (67% identical), TRAV8-7 (66% identical), TRAV8-6 (65% identical), TRAV8-2 (65% identical), TRAV3 (55% identical), TRAV16 (48% identical).